LYN (LYN proto-oncogene, Src family tyrosine kinase)
Diseases named in the same sentence as LYN in open-access papers (continued):
Sharing a sentence is not in itself a finding about the gene and the disease.
leukemia (13 papers, 2015 to 2024). A malignant (clonal) hematologic disorder, involving hematopoietic stem cells and characterized by the presence of primitive or atypical myeloid or lymphoid cells in the bone marrow and the blood. "Previous studies have largely focused on LYN function in hematopoietic cells and leukemia, and persistent activation and/or deregulation of LYN has been associated with imatinib resistance in BCR-ABL+ leukemia." (PMID 30590041, 2018). "LYN-deficient fibroblasts show markedly reduced leukemia feeding capacity in vitro." (PMID 36899005, 2023). "LYN, a member of the Src receptor kinase family, has been extensively studied in BCR-ABL+ leukemia, where its persistent activation is linked to imatinib resistance." (PMID 38256136, 2024). "Together, our findings suggest that LYN is essential for rewiring fibroblasts towards a leukemia-supportive phenotype." (PMID 36899005, 2023). "This illustrated that the leukemia-supportive LYN effects in BMSC were at least partially mediated by c-JUN." (PMID 36899005, 2023). "LYN-defective fibroblasts acquire leukemia-suppressive properties, mediated—at least in part—by a remodeled matrix and the increased expression of THBS1, which induces CLL cell death." (PMID 36899005, 2023). "This suggests a potential impact of stromal LYN on T-cell-mediated immune response towards leukemia, driven by changes in cytokine secretion." (PMID 36899005, 2023). "FYN is a major downstream target of ABL1 in human leukemias and LYN signaling promotes resistance to ABL1 inhibitors." (PMID 38047771, 2023). "In acute myeloid leukemia (AML), we found that APOC2 acts with CD36 to promote leukemia growth by activating the LYN-ERK signaling." (PMID 37226083, 2023). "Regarding signaling through a family of different Src kinases (including LYN and SRC), these are expressed in AML and their phosphorylation regulates leukemia cell proliferation and survival (including through LYN mediating mTOR activation)." (PMID 35053339, 2022). "Evidence is mounting that strongly implicates an important role for LYN in several types of leukemia and lymphoma, particularly in B-ALL, where studies have confirmed the overexpression of LYN and its critical role in maintaining proliferation and antiapoptotic pathways in leukemic cells." (PMID 36765939, 2023). "By contrast, mice bearing constitutively active LYN mutations did not exhibit leukemia development." (PMID 30428571, 2018). "Our results are in line with previous reports on other diseases proposing a high LYN mRNA activation level as a vital indicator for drug sensitivity to DASA, such as in lung cancer and leukemia." (PMID 38739359, 2024). "In leukemia, HSP90 has been shown to bind to LYN in B-chronic lymphoblastic leukemia (B-CLL) and the use of 17-AAG destabilized the binding of HSP90-LYN in vitro, initiating cell apoptosis." (PMID 33737511, 2021). "Concomitantly, EC-7072 was able to downregulate the total amount of LYN, PLCγ2 and STAT3 in CLL cells, further reinforcing the broad transcriptional reprogramming of primary leukemia cells from patients with CLL upon exposure to the compound." (PMID 31681329, 2019). "Together the results reported here support the concept that LYN modulates the polarization of stromal fibroblasts and induces an inflammatory CAF phenotype, thus rewiring essential components of a supportive microenvironment niche for leukemia cells." (PMID 36899005, 2023).
autoimmune disease (11 papers, 2011 to 2025). A disorder resulting from loss of function or tissue destruction of an organ or multiple organs, arising from humoral or cellular immune responses of the individual to their own tissue constituents. "Interestingly, LYN deficiency leads to a 20-fold increase of BM PCs and induces autoimmune disease in mouse models." (PMID 37355988, 2023). "The increased expression of CXCL9 and CXCL11 may also excessively activate the hippocampal type Th1 immune and inflammatory response and trigger autoimmune diseases, but the upregulated expression of LYN (ratio: 2.06) eliminated our concerns." (PMID 31031647, 2019). "LYN, one of the SFK members, is an important regulator of autoimmune diseases such as asthma and psoriasis." (PMID 26065685, 2015).
colorectal cancer (8 papers, 2015 to 2023). A primary or metastatic malignant neoplasm that affects the colon or rectum. "In contrast, in colorectal cancer, LYN overexpression was positively correlated with tumour grade, stage, lymph node involvement/distant metastasis and lower patient survival." (PMID 29937990, 2018). "LYN promotes colorectal cancer development via CD24-mediated ERK1/2 activation, and dasatinib is effective in treating metastatic prostate cancers harboring activated LYN." (PMID 27756880, 2016). "In addition, the regulation of LYN by DNA methylation was demonstrated in both colorectal cancer and Ewing’s sarcoma, and LYN methylation has been observed in some hematopoietic and non-hematopoietic cell lines." (PMID 26460485, 2015).
lung carcinoma (8 papers, 2013 to 2024). "In a study of lung cancer cell lines using quantitative phosphoproteomics, approximately 40 different kinases were identified as dasatinib targets, including the SFKs LYN, SRC, YES, FYN, and LCK." (PMID 27756880, 2016). "The presence of LCK and LYN in clusters containing proteins commonly phosphorylated in lung cancer suggest potential pathways of signal transduction." (PMID 23300999, 2013). "In particular, SRC was overexpressed in most lung cancer samples in addition to either LYN or FYN." (PMID 29937990, 2018). "The functions of LYN have been investigated primarily in hematopoietic cells, but several recent studies have suggested that LYN plays a critical role in the development and progression of colon, prostate, breast, and lung cancers." (PMID 27756880, 2016). "In general, circSMARCA5 has a significant relationship with DFS, tumor size, LYN metastasis, TNM stage, and CEA of lung cancer and can also be used as an independent predictor of lung cancer prognosis." (PMID 35712125, 2022). "This was clinically relevant as LYN and FYN are also overexpressed in lung cancer clinical specimens." (PMID 29937990, 2018). "As SRC expression in lung cancer has previously been examined we focused on the expression of FYN and LYN using two different tissue micro arrays comprising 146 (TMA1) and 138 (TMA2) surgically resected NSCLC cases." (PMID 29937990, 2018). "The results of immunohistochemical analysis showed that compared with the stage I lung cancer group, the expression levels of COPG2IT1 and HLA.DQA1 in the stage III lung cancer group were significantly increased, and the expression levels of LYN, C3 and TNFRSF17 were significantly decreased." (PMID 33215029, 2020).
atherosclerosis (7 papers, 2016 to 2025). A disease characterized by the build-up of fatty material and calcium deposition in the arterial wall resulting in partial or complete occlusion of the arterial lumen. "Pathway “Lipid and Atherosclerosis” and related genes, for example, LYN, SELP, OLR1." (PMID 40621499, 2025). "Interestingly, we observed that the immunoinflammatory biological processes and atherosclerosis deterioration-related pathways shared some common genes, including LYN, PTGIR, F11R, and C3AR1." (PMID 34095251, 2021). "LYN is the src family gene, and it is revealed that the scavenger receptor CD36 could bind to the oxidized LDL, thus activating LYN by the recruitment of Na/K-ATPase-LYN complex and enhancing the development of atherosclerosis." (PMID 34688276, 2021). "This study identified SYK, LYN, PTPN6 and the “FcεRI-mediated signaling pathway” as potential candidate players involved in the pathogenesis of atherosclerosis." (PMID 26742467, 2016). "Several other nodes in the module (e.g., LYN and SYK) are druggable, have atherosclerosis phenotypes in mice, and have preferable target tissues and thus may be interesting targets for new CAD therapies." (PMID 29467471, 2018). "The analysis revealed that a similar representation of the gene expression patterns of our candidate DEGs was seen in the dataset GSE28829, suggesting that VAV1, SYK, LYN and PTPN6 genes may play an important role in progression of atherosclerosis." (PMID 26742467, 2016).
COVID-19 (7 papers, 2020 to 2025). A disease caused by infection with severe acute respiratory syndrome coronavirus 2. "We did not observe any significant alteration in the expressions of CD74 and LYN in the whole blood of hospitalized COVID-19 patients compared to the Healthy group." (PMID 36611805, 2022). "We observed that the COVID-19 ICU patients had activated T cell and B cell signaling characterized with activation of the tyrosine kinases LCK, LYN, and SYK." (PMID 38389037, 2024). "The results showed that most of the genes, as in the discovery set (except CD38, LYN, and ITGAX), were significantly upregulated in patients with severe COVID-19 (p < 0.05)." (PMID 36052061, 2022). "There was a positive correlation between COVID-19-related protein RPL23 and LYN." (PMID 35720320, 2022). "Among our results, several immune-related pathways including those activated by Fc-epsilon-related signaling (LYN and PI3K), NIK/NF-κB (ub, CUL1, SKP1, proteasome, and NFKB2), and via C-type lectin receptor pathways (PTPN11 and CARD9) were enriched in the COVID-19 lungs." (PMID 33060566, 2020).
glioma (7 papers, 2009 to 2024). A benign or malignant brain and spinal cord tumor that arises from glial cells (astrocytes, oligodendrocytes, ependymal cells). "Transcriptional data was mined from two publicly available datasets, TCGA and CGGA, and used to investigate the correlation between LYN and clinical characteristics including patient prognosis, somatic mutation, and immune infiltrating features in gliomas." (PMID 35186945, 2021). "ROC curve proved the predictive value of LYN expression in glioma patients with IDH mutation or IDH wildtype in TCGA and CGGA." (PMID 35186945, 2021). "LYN can be a potential diagnostic marker and immunotherapy marker in gliomas." (PMID 35186945, 2021). "LYN was associated with malignancy of gliomas and served as a prognostic marker of glioma patients." (PMID 35186945, 2021). "Glioma samples with CN loss expressed significantly higher level of LYN mRNA than diploid." (PMID 35186945, 2021). "Besides, LYN was enriched in CL and ME subtype of gliomas, which indicated worse survival, and LYN was associated with 1p19q non-codeletion and unmethylated MGMT promoter, both of which predicted worse survival in glioma patients." (PMID 35186945, 2021). "We demonstrated that patients with higher LYN expression possessed poor overall survival and had greater risks of progression into a more-aggressive type of glioma." (PMID 37416766, 2023). "A global CNA profile was obtained in glioma samples with low LYN expression and glioma samples with high LYN expression." (PMID 35186945, 2021). "Patients with recurrent gliomas were detected with higher level of LYN expression compared with patients with primary gliomas." (PMID 35186945, 2021). "Our study demonstrates that glioma-derived NLGN3 promotes glioma progression by upregulating activity of LYN and ADAM10, which in turn promote NLGN3 cleavage to form a positive feedback loop." (PMID 34485271, 2021). "Taken together, we described the characteristics of LYN in gliomas based on bioinformatics analysis of several datasets." (PMID 35186945, 2021). "LYN positively correlated with classical immune checkpoint molecules in glioma samples in TCGA and CGGA." (PMID 35186945, 2021). "LYN showed higher expression in glioma patients with progressive disease than in glioma patients with complete remission." (PMID 35186945, 2021). "LYN protein level was also found to be upregulated with increase of WHO grades based on the IHC staining results of glioma samples (n = 40) from the Xiangya hospital cohort." (PMID 35186945, 2021). "In the present research, we found that secreted NLGN3 in cell culture medium promoted the level of LYN phosphorylation in glioma cells." (PMID 34485271, 2021). "Glioma samples with high LYN expression had frequent amplification of chr7 and deletion of chr10, while glioma samples with low LYN expression had frequent deletion of 1p and 19q." (PMID 35186945, 2021). "In glioma samples with high LYN expression, oncogenic driver genes such as EGFR (7p11.2) and CDK4 (12q14.1) were frequently amplified, while tumor suppressor gene PTEN (10q23.31) and CDKN2A (9p21.3) were frequently deleted." (PMID 35186945, 2021). "LYN predicted malignant gliomas and served as a prognostic marker indicating worse survival of glioma patients." (PMID 35186945, 2021). "Here, we explored the expression pattern of Lck/yes-related protein tyrosine kinase (LYN) in gliomas and assessed its value as an immunotherapy biomarker." (PMID 35186945, 2021). "In summary, in the glioma microenvironment, NLGN3 secreted by neurons and glioma cells activates LYN and upregulates ADAM10 expression, which can cleave NLGN3 to promote its secretion." (PMID 34485271, 2021).
glioma (continued). "The activation of the LYN signaling pathway in glioma promotes the proliferation and metastasis of tumor cells." (PMID 34485271, 2021). "LYN has been reported to promote the proliferation and migration of glioma cells and inversely correlates with patient survival." (PMID 35186945, 2021). "High expression level of LYN was observed in advanced gliomas and other cancer types, which predicted a worse prognosis." (PMID 35186945, 2021). "Based on large-scale bioinformatics analysis, we comprehensively delineated the clinical characteristic landscape of LYN in the immune infiltrating microenvironment of gliomas." (PMID 35186945, 2021). "There are nine members in the family, four of which (Src, FYN, YES, and LYN) are expressed in human gliomas." (PMID 31114755, 2019). "Additionally, LYN expression is relatively higher in both low-grade glioma (LGG) and glioblastoma (GBM)." (PMID 37416766, 2023). "Besides, LYN expression correlated with inflammatory signature genes in glioma samples and GBM samples in TCGA and CGGA." (PMID 35186945, 2021). "Several studies have shown that LYN activation can promote the progression of human glioma." (PMID 34485271, 2021). "However, there is a need for research to investigate LYN as a potential immune checkpoint molecule, which can promote the clinical management of glioma patients receiving immunotherapy." (PMID 35186945, 2021). "LYN expression was more enriched in unmethylated glioma samples." (PMID 35186945, 2021). "Besides, LYN facilitated the establishment of an immune-suppressive and favorable glioma microenvironment." (PMID 35186945, 2021). "The expression level of LYN also stratified glioma patients’ survival in the Xiangya cohort." (PMID 35186945, 2021). "Our work revealed that LYN was upregulated in higher grade gliomas." (PMID 35186945, 2021). "Moreover, LYN facilitated the establishment of an immune-suppressive and favorable glioma microenvironment." (PMID 35186945, 2021). "Taken together, these results indicated that LYN regulated glioma cell progression and proliferation, and high LYN expression could predict the survival rate of glioma patients." (PMID 35186945, 2021). "In this study, we speculated that LYN may be another promising biomarker for immunotherapy in glioma patients." (PMID 35186945, 2021). "In addition, we found that the expression of ADAM10 in glioma and normal brain tissue was positively correlated with the levels of LYN and NLGN3." (PMID 34485271, 2021). "Additionally, GSVA in KEGG and GSEA showed that LYN negatively regulated the immune system in gliomas and promoted the proliferation of glioma cells." (PMID 35186945, 2021). "LYN expression was positively associated with a variety of immune infiltrating cell types responsible for an anti-tumor response in GBM samples and glioma samples." (PMID 35186945, 2021). "The NLGN3/LYN/ADAM10 axis promotes glioma progression via a positive feedback loop." (PMID 34485271, 2021). "This study further showed that LYN was involved in the glioma immune microenvironment." (PMID 35186945, 2021). "In this study, LYN expression was observed in IDH wild-type gliomas." (PMID 35186945, 2021). "Taken together, these results revealed the immuno-suppressive role played by LYN in gliomas." (PMID 35186945, 2021). "Moreover, LYN expression in glioma patients could significantly predict anti-PD-1 and anti-CTLA-4 immunotherapy responses based on the TIDE algorithm." (PMID 35186945, 2021). "Notably, we found the co-expression pattern of LYN and PD-L1 in glioma microenvironment." (PMID 35186945, 2021). "Besides, LYN was found to have a positive correlation with estimate score, immune score and stromal score, all of which were negatively correlated with the prognosis of glioma patients." (PMID 35186945, 2021).
glioma (continued). "In the present research, we elucidated the functional effects of glioma-derived NLGN3 and discussed the feedback regulation pathway of LYN and NLGN3 in glioma cells to further improve our understanding of glioma progression." (PMID 34485271, 2021). "LYN was found to positively correlate with immune score, stromal score, and ESTIMATE score in GBM samples and glioma samples." (PMID 35186945, 2021). "Knockdown of endogenous NLGN3 significantly reduced the proliferation, migration, and invasion of glioma cells and down-regulated the activity of the PI3K-AKT, ERK1/2, and LYN signaling pathways." (PMID 34485271, 2021). "Moreover, LYN expression was negatively related to progression-free interval (PFI) and disease-specific survival (DSS) in glioma patients." (PMID 35186945, 2021). "LYN also positively correlated with various immune infiltrating cells, including Tregs, M2 macrophage, and MDSC, which contribute to an immunosuppressive microenvironment in gliomas." (PMID 35186945, 2021). "Furthermore, LYN showed high expression in histopathologically malignant glioma samples and 1p/19q non-codeletion glioma samples." (PMID 35186945, 2021).
lymphoma (7 papers, 2015 to 2024). A malignant (clonal) proliferation of B- lymphocytes or T- lymphocytes which involves the lymph nodes, bone marrow and/or extranodal sites. "Previous studies have demonstrated that lymphoma cells can unlock this oncogenic strategy through CD79B/A mutations, which result in increased BCR surface levels through hindered BCR internalization and loss of negative regulation by phosphorylation by LYN." (PMID 38630892, 2024). "Lymphomas resistant to proteasome inhibitors show increased expression in BCR and activation of the BCR signaling pathway enhances the activity of SFK, especially LYN, and downstream kinases PI3K/AKT/mTOR in proteasome inhibitor-resistant lymphoma cells." (PMID 36765939, 2023). "In summary, in human lymphoma cells LUX and IB have quite distinct mechanistic effects on the phosphorylation of BTK and its activity, and on the upstream kinases SYK and LYN, and the adaptor protein BLNK against which LUX is very potent and IB had little effect." (PMID 36888611, 2023).
acute myeloid leukemia (6 papers, 2017 to 2023). Acute myeloid leukemia (AML) is a group of neoplasms arising from precursor cells committed to the myeloid cell-line differentiation. "LYN has the capacity to stabilize focal adhesion complexes and its overexpression were associated with better OS in acute myeloid leukemia." (PMID 33038770, 2020). "The differentially expressed transcripts and proteins, predicted transcriptional factors, and key molecules such as HIC1, CEBPB, LYN, and PARP1 may be considered as potential targets for differentiation therapy of acute myeloid leukemia." (PMID 34207065, 2021).